INS (insulin)
Diseases named in the same sentence as INS in open-access papers (continued):
Sharing a sentence is not in itself a finding about the gene and the disease.
infection (continued). "Infection of mice with T. spiralis and T. pseudospiralis has been reported to cause an initial decrease in insulin concentration, which is restored back to normal." (PMID 35923890, 2022). "According to this literature research risk factors for the development are infection, perioperative fasting, surgical stress, and insulin dose reduction." (PMID 35402477, 2022). "This persistent infection was characterized by molecular detection of only 5′TD RNA forms that were associated with dystrophin cleavage in the heart and insulin production impairment in beta-pancreatic cells." (PMID 36016091, 2022). "The beneficial effect of LF infection, in reducing the morbidity associated with MS, seems to be, largely due to the upregulation of incretins, which increase both insulin secretion and decrease IR." (PMID 36482987, 2022). "Our main findings indicate that among patients undergoing elective surgery, preoperative low-dose carbohydrate loading has been found to be associated with insulin resistance and postoperative infection rates." (PMID 36505254, 2022). "Similar to findings in Saudi Arabia, where 9% and 29% of participants related DKA to infection and febrile illness, and 32% of them recognized missed insulin dose as a cause." (PMID 35846869, 2022). "The reduction in doctor visits among the older and insulin-prescribed patients due to the increased risk of infection was inevitable in this pandemic but was surely alarming because they require careful monitoring." (PMID 34841037, 2021). "When experiencing a reduction in insulin sensitivity of 80% due to one of many possible causes (puberty, pregnancy, infection, increased adiposity), an individual would be predicted to mount a five-fold greater insulin response." (PMID 32405763, 2021). "The transdermal route is an interesting choice for insulin delivery, as this approach would mitigate the pain and infection risk related to subcutaneous injections." (PMID 33466845, 2021). "Physiologic stressors like surgery and infection can increase stress hormones like cortisol, adrenaline causing further insulin resistance and protein catabolism from alpha and beta receptor stimulation." (PMID 34123681, 2021). "Risk factors leading to DKA among established cases include insulin omission (73%), infection (16%), insulin pump failure (1.2%), fasting (0.6%), improper insulin injection technique (0.6%), and other causes (0.6%)." (PMID 33868185, 2021). "Transdermal drug delivery presents exciting possibilities, as it eliminates the pain and risk of infection associated with subcutaneous insulin injections, ensures patient compliance, and provides a controlled release of insulin." (PMID 33466845, 2021). "The other most common causes of DKA presentation were; insulin omission (34.1%), insulin pump dysfunction (14.9%) and precipitating factors such as infections (8.2%)." (PMID 31722517, 2020). "Regardless, the intervention induced significant changes in fitness, and small non-significant changes in body composition which was related to improved glucose control and insulin sensitivity, and neutrophil functions in a high infection risk population." (PMID 32431698, 2020). "Although most studies in the field consistently agree that T1D causes a higher susceptibility to different types of infections, the modulatory role of insulin seems to differ according to the inflammatory stimulus to which the subject is exposed." (PMID 33312173, 2020). "In patients with a previously diagnosed T1DM, adolescent patients are at risk, and the most common cause is skipping the insulin dose, technical problems with the pump in patients using an insulin pump, and infection." (PMID 33178500, 2020). "In a study from Libya, 35% of participants missed their insulin dose and underlying infection was present in 20% DKA patients." (PMID 31372327, 2019). "Infections (36.5%) and inadequate insulin dose (22.5%) were frequently seen as the predisposing factors." (PMID 31372327, 2019).
infection (continued). "The two most frequent factors predisposing to the development of DKA are an underlying infection and insufficient insulin therapy including skipped/missed doses or taking less than the therapeutic dose." (PMID 31372327, 2019). "The two most frequently encountered risk factors precipitating to DKA are missed insulin dose and presence of infection." (PMID 31372327, 2019). "In parallel, Ad-p21 infection caused lower circulating glucose and insulin concentrations under fasting conditions and stimulated in vitro insulin-stimulated 2-deoxy-glucose uptake into white adipose tissue (WAT) and muscle (left)." (PMID 31097688, 2019). "Telomere shortening with early PN was independent of post-randomisation factors affected by early PN, including longer length of PICU stay, larger amounts of insulin and higher risk of infection." (PMID 29463275, 2018). "Its pathophysiology is complex and includes the loss of pancreatic islet cells, leading to both insulin and glucagon deficiency, and fluctuating insulin resistance caused by chronic and acute inflammation and infection." (PMID 30021636, 2018). "The early PN effect on telomere length was also independent of other post-randomisation factors affected by early PN, including the larger amount of insulin given and the higher risk of acquiring a new infection in the PICU." (PMID 29463275, 2018). "The use of this protocol vs. subcutaneous insulin according to glucose levels (historical control) was associated with reduced rates of infection and death in about 50% of patients." (PMID 28725272, 2017). "Patients are currently educated to replace their CCs every 2 to 3 days to minimize the risk of infection and because insulin absorption from the subcutaneous tissue into the circulation becomes more variable and less reliable over time." (PMID 28981324, 2017). "The infection by Pseudomonas causes reduction of insulin secretion while Enterobacter and Staphylococcus determined an increase in insulin secretion." (PMID 27631977, 2016). "DM was also shown to be a risk factor for the development of a postoperative infection, in all likelihood because of the difficulty of effective glucose control postoperatively related to a decrease in insulin secretion and an increase in insulin resistance." (PMID 27777946, 2016). "Suppression of the insulin signal appears to induce physiological responses promoting resistance to low temperature, oxidative stress, and pathogenic infections." (PMID 23885240, 2013). "In turn, the insulin signal induces hemocyte (immune cells) production, which serve as the first line of defense against pathogenic infections." (PMID 23885240, 2013). "When forkhead transcription factor (daf-16), which is negatively regulated by the insulin signaling pathway in C. elegans, is suppressed the worms exhibit increased susceptibility to infection by pathogenic bacteria." (PMID 23885240, 2013). "The subjects with previous infection have enhanced weight loss, bright liver disappearance, and recovery of insulin sensitivity." (PMID 24324491, 2013). "Genetic experiments suggested that this infection phenotype is likely caused by modulation of the DAF-2 insulin/IGF-1 signalling pathway." (PMID 22672310, 2012). "Another study found that the risk of infection and other serious life-threatening complications is 36% to 38% higher in diabetics and that insulin-treated diabetics had the highest risk of serious complications." (PMID 22082355, 2011). "The study of glucose transport and regulation by insulin in lymphocytes is important, since the way they increase inflammation and susceptibility to infections are common in MS." (PMID 21044347, 2010). "Intensive insulin therapy was positively associated with survival and a reduced incidence of infections." (PMID 20137090, 2010). "Infection by this strain also caused functional impairment that significantly affected insulin response to high glucose at 48 hours post infection (p<0.001)." (PMID 11467407, 2000).
infection (continued). "The aim of the present review is to understand the intricate interaction between endogenous hormones—including cortisol, melatonin, thyroid hormones, sex hormones, and insulin—and the immune response to an hMPV infection by reviewing the complex molecular mechanisms associated with this interplay." (PMID 40176892, 2025). "Infection of COVID‐19 by the body could lead to a massive release of proinflammatory cytokines, resulting in the chronic inflammatory reaction, and decreasing insulin secretion, thereby aggravating the risk of DM." (PMID 41476996, 2025). "A survey-based study conducted in Makkah, Saudi Arabia, found that the overall awareness of patients and their caregivers regarding DKA is poor (67%), with only 16% linking infections as a risk factor and only 29.3% identifying missing insulin doses as a main cause of DKA." (PMID 41375809, 2025). "Additionally, identifying and treating underlying triggers, such as infections, dehydration, or recent reductions in insulin therapy, is crucial." (PMID 40125161, 2025). "A review by Peters et al12 demonstrated that 7 of the 13 episodes of eDKA due to canagliflozin were in patients with underlying T1DM and that infection, reduced food intake, increased physical activity, and large recent reductions in insulin doses served as precipitants of eDKA." (PMID 40677793, 2025). "Several high-quality articles have confirmed that oral administration of carbohydrate-containing clear liquids reduces postoperative insulin resistance and risk of infection, and their administration ≤2 h before surgery is overwhelmingly supported in the literature." (PMID 39617150, 2025). "Nanoparticles for the oral administration of insulin represent a long-sought alternative to the frequent SC injections that diabetic patients must undergo, which cause discomfort, pain, suffering, and the possibility of local infections." (PMID 39000136, 2024). "Moreover, concurrent infection with S. stercoralis or multiple GINs is associated with elevated levels of serum type 2 cytokines, reduced circulating insulin levels, and increased insulin sensitivity, and these effects can be replicated in mouse models." (PMID 38277692, 2024). "However, because infection causes insulin resistance in skeletal muscle cells, the pancreatic insulin output is increased to compensate for the reduced glucose uptake by the muscle." (PMID 39107476, 2024). "SARS-CoV-2 can invade and replicate in human islet culture, and infection causes morphological, transcriptional, and functional alterations, such as decreased insulin-secretory granules in β cells and impairment of glucose-stimulated insulin secretion." (PMID 37124033, 2023). "Bartlett, Slentz reported that after 10 weeks of high-intensity interval exercise training in diabetic patients, neutrophil dysfunction, glucose control, and insulin sensitivity were improved, while ROS production was significantly reduced, thus decreasing the risk of infections and disease." (PMID 37893490, 2023). "Correspondingly, infection with an adenovirus encoding Usp2 shRNA significantly lowered blood glucose, blood insulin, hepatic glycogen content, and insulin sensitivity in high fat diet–fed mice, suggesting that USP2 plays a role in aggravating T2DM pathogenesis." (PMID 36834633, 2023). "It occurred due to the observation of infection incidences that could increase blood glucose levels in association with abnormal alterations in the insulin-to-carbohydrate ratio." (PMID 36572938, 2022). "Because infected flies exhibit starvation-like effects on metabolite stores and insulin-pathway activity, we tested whether hyperactivity during infection was linked to infection-induced starvation signalling." (PMID 36129961, 2022). "The underlying cause was insulin cessation in 86.6%, followed by infection at 38%." (PMID 35846869, 2022).
infection (continued). "Although people nowadays can use insulin pumps with integrated blood glucose sensing systems as an automatic way to monitor and control their blood glucose, there is still an increased risk of infection." (PMID 35062385, 2022). "This review explores potential interactions between infectious agents and insulin and leptin signaling pathways, and discuss possible mechanisms underlying the relationship between infection, metabolic dysregulation, and brain disorders, particularly focusing on the roles of insulin and leptin." (PMID 34795562, 2021). "Indeed, although in adult flies the metabolic role of DILPs appears complex, a reduction of expression of these insulin analogs has been suggested to cause infection-induced wasting." (PMID 32839462, 2020). "Others have observed that Gram-negative infections can activate the Toll pathway, and Toll pathway activation has been associated with effects on the insulin signaling pathway that could drive the metabolic effects we see in this infection." (PMID 32733472, 2020). "Infections and missed insulin dose were frequently seen as the predisposing factors." (PMID 31372327, 2019). "Underlying infections and inadequate insulin regimen predispose to acute DKA attack." (PMID 31372327, 2019). "However, multiple daily insulin injection is associated with local infection, hypertrophy, fat deposits at injection sites, and trypanophobia." (PMID 31756981, 2019). "In our study, underlying infections were more common than inadequate insulin dose." (PMID 31372327, 2019). "Chronic insulin exposure quantitatively alters the lipid content of mast cells, causes a steatosis-like accumulation of lipid bodies similar to that observed in neutrophils and macrophages under conditions of infection." (PMID 31311389, 2019). "Similarly, infection with soil-transmitted helminths including A. lumbricoides, T. trichiura, and N. americanus has been associated with increased insulin sensitivity." (PMID 30298071, 2018). "Higher infection among insulin users may be linked to more frequent exposure to insulin injections and finger sticks for monitoring blood glucose where unsafe injections or sharing contaminated equipment promote infection." (PMID 27464785, 2016). "These lines of evidence suggest that insulin/FOXO signaling in diapausing insects may be linked to induction of immune effectors that enhance resistance to pathogenic infection." (PMID 23885240, 2013). "Therefore, glycemic fluctuations during insulin therapy may trigger immune dysregulation, while its effects on inflammation and wound healing may inadvertently increase infection risk, and this evidence confirm our results." (PMID 40863575, 2025). "A 2022 meta-analysis demonstrated that intensive insulin therapy in abdominal and cardiac surgeries significantly reduced the incidence of surgical site infections, while another study suggested that maintaining perioperative blood glucose levels below 150 mg/dl decreases infection risk." (PMID 41321926, 2025). "However, there is concern that insulin therapy may increase the risk of severe infections due to its anti-inflammatory effects and metabolic abnormalities." (PMID 40863575, 2025). "Additionally, insulin infusion is less invasive, easier to initiate, and associated with fewer complications compared to plasmapheresis, which requires hemodialysis access and carries risks such as bleeding and infection." (PMID 39958046, 2025). "This might be due to the fact that infection causes the body to produce of hormones like adrenaline and cortisol, which hinder the effect of insulin, or infection causes the body to release cytokine and inflammation that end up with disturbance of insulin action (insulin resistance)." (PMID 38468250, 2024). "Additionally, infection-caused inflammation could lead to both decreased insulin secretion and heightened cell resistance to insulin." (PMID 38787222, 2024).
infection (continued). "However, as the diabetic person needs to repeat insulin injection continuously in life time and as such insulin injection might cause other problems specially bruising, soreness, infection, redness, irritation occurs at the site of injection." (PMID 27226415, 2016). "Therefore, high insulin levels associated with endotoxaemia and infection may have influenced the down-regulation of adipoR1 gene expression observed in our study." (PMID 26618091, 2015). "Similarly, depleted protein storage and severe surgical stress after oesophageal resection may impair the immune response postoperatively and thus increase the risk for postoperative infection, which may be ameliorated by insulin." (PMID 15566589, 2004). "Post-burn hypermetabolism and infection drove protein catabolism, insulin resistance, and tissue glucose underutilization." (PMID 41559973, 2026). "Background/Objectives: Skin disinfection before insulin administration is widely regarded as essential for preventing injection-site infection." (PMID 41295816, 2025). "Infection and postoperative status stimulate the secretion of glucagon, cortisol, and catecholamines, thereby promoting insulin resistance, lipolysis, and ketogenesis despite normal blood glucose levels." (PMID 40502910, 2025). "The Omnipod solves several problems shared by plerixafor and insulin, including frequent dosing due to short half-lives, high cost from compounding sterile syringes, inconvenience and potential for infection from frequent injections." (PMID 40330596, 2025). "Prompt fluid resuscitation, insulin therapy, infection management, and a carefully controlled steroid taper facilitated full neurological and metabolic recovery." (PMID 41541983, 2025). "The present review explores the role of endogenous hormones, such as cortisol, melatonin, thyroid hormones, sex hormones, and insulin, in the modulation of the immune response to a human metapneumovirus (hMPV) infection." (PMID 40176892, 2025). "AS1-4 infection was able to induce abnormal glycogen deposition and exhibit a profound effect on the insulin signaling pathway and steroid biosynthesis in TCFs." (PMID 41300278, 2025). "The most common administration method for insulin is subcutaneous injection, but it leads to decreased compliance and tissue infections due to the need for multiple daily injections." (PMID 40292663, 2025). "Several patients have been observed to develop tissue necrosis and severe infection around insulin injection sites due to insulin amyloids." (PMID 40723866, 2025). "Common precipitating factors such as infection, insulin pump malfunction, or psychosocial stress should first be excluded." (PMID 41536411, 2025). "A final pathway involves pathogen-derived molecules or infection-related tissue effects that impair insulin signaling or organ function." (PMID 41583303, 2025). "In conclusion, the risk of recurrent eDKA was increased in our patient due to decreased endogenous insulin production, decreased oral intake, and the presence of diabetic myonecrosis with superimposed infection." (PMID 40677793, 2025). "An unusual case involved a 37-year-old female who developed an abdominal wall infection adjacent to G adiacens due to incorrect insulin injection behavior." (PMID 40355223, 2025). "The interplay between host carbohydrate metabolism and infection appears integral to insect permissiveness and persistence, with insulin signaling contributing to metabolic regulation." (PMID 40017802, 2025). "Triggers for euglycemic DKA include infection, dehydration, fasting, surgery, or reduced insulin therapy, all of which exacerbate ketone production and acid-base disturbances." (PMID 40125161, 2025). "During critical stages of infection, the interplay between viral replication and immune activation can further elevate glucose levels and reduce insulin sensitivity, compounding metabolic complications." (PMID 40564201, 2025).